CHGA (chromogranin A)
Diseases named in the same sentence as CHGA in open-access papers (continued):
Sharing a sentence is not in itself a finding about the gene and the disease.
Insulin resistance (2 papers, 2022 to 2025). Increased resistance towards insulin, that is, diminished effectiveness of insulin in reducing blood glucose levels. "Thus, the higher circulation level of CHGA in Reg1cp-mutRIP+ mice might be cause by the hormone imbalance induced by insulin resistance." (PMID 36302749, 2022). "Elevated levels of CHGA and pancreastatin are associated with type 2 diabetes, while the absence of these peptides reduces insulin resistance in mice." (PMID 41018225, 2025).
mesenchymal neoplasms (2 papers, 2022 to 2025). "Regarding Case 2, it is noteworthy that it labeled not only for synaptophysin but also for chromogranin-A, a combination that we encountered only rarely in mesenchymal neoplasms with neuroendocrine features (data not shown)." (PMID 34228212, 2022).
metastatic carcinoma (2 papers, 2018 to 2022). A carcinoma which has spread from the original site of growth to another anatomic site. "Immunohistochemically, primary and metastatic cancer cells were diffusely positive for chromogranin A and the estrogen receptor (Allred's total score: 8) and focally reactive for synaptophysin and the progesterone receptor (total score: 5)." (PMID 36572422, 2022).
multiple myeloma (2 papers, 2021 to 2022). "Apart from being secreted from neuroendocrine tissues and nerve endings, ChgA is widely distributed in the secretory granules of the skin, sensory organs, and myocardium, and novel data suggest that ChgA is preferentially processed in the bone marrow of multiple myeloma patients." (PMID 34944578, 2021).
multiple sclerosis (2 papers, 2009 to 2018). A progressive autoimmune disorder affecting the central nervous system resulting in demyelination. "Elevated levels of Chromogranin A in CSF from patients were associated with Astrocytes of Multiple Sclerosis White Matter Lesions." (PMID 29479521, 2018).
non-small cell lung carcinoma (2 papers, 2006 to 2010). A group of at least three distinct histological types of lung cancer, including non-small cell squamous cell carcinoma, adenocarcinoma, and large cell carcinoma. "Chromagranin A (ChgA; parathyroid secretory protein 1) is an established tissue marker associated with neuroendocrine differentiation – and indicative of outcome – in non-small cell lung carcinoma." (PMID 17173689, 2006).
ovarian neoplasm (2 papers, 2025). A benign, borderline, or malignant neoplasm involving the ovary. "This highlights the importance of assessing neuroendocrine markers, such as chromogranin A, synaptophysin, and Ki-67; when evaluating atypical ovarian tumors biologically, O-NENs encompass a wide spectrum of behaviors." (PMID 41464736, 2025). "Immunohistochemical markers such as synaptophysin, chromogranin A, and CD56 remain critical for accurate diagnosis and differentiation from other ovarian neoplasms." (PMID 40490785, 2025).
prediabetes (2 papers, 2023 to 2025). "Determination of ChgA concentration in patients’ sera may therefore potentially serve as an important biomarker of prediabetes." (PMID 36983153, 2023).
sarcoma (2 papers, 2007 to 2022). A usually aggressive malignant neoplasm of the soft tissue or bone. "Besides neural cell adhesion molecules (CD56), other neuroendocrine markers synaptophysin (Syn), neuron-specific enolase (NSE), and chromogranin A (CgA) are often used in differential diagnosis of sarcoma." (PMID 35372059, 2022). "Histopathology revealed characteristic GCTs with positive immunostaining for neural marker (S-100) and negative immunostaining for epithelial (cytokeratin, Cam 5.2, AE/A13), neuroendocrine (neuron specific enolase, chromogranin A, and synaptophysin) and sarcoma (desmin, vimentin) markers." (PMID 17355632, 2007).
signet ring cell carcinoma (2 papers, 2019 to 2021). A usually aggressive, poorly differentiated invasive adenocarcinoma characterized by the presence of malignant glandular cells in which the nucleus is pressed to one side by the presence of intracytoplasmic mucus. "In another study, the neuroendocrine marker chromogranin A was expressed in an important portion of signet-ring cell carcinomas, and patients had better prognoses if chromogranin A was expressed in the cancer cells, indicating that this expression was lost during the process of malignancy." (PMID 34202596, 2021). "One study limited to staining for chromogranin A, a sensitive marker of neuroendocrine differentiation, also demonstrated focal or diffuse immunopositivity in 37.3% of gastric signet ring cell carcinomas, including 6% with staining in more than half of neoplastic cells." (PMID 31832022, 2019).
sympathetic paraganglioma (2 papers, 2012 to 2024). A benign or malignant paraganglioma arising from the chromaffin cells of the paraganglia that are located along the sympathetic nerves. "Sympathetic paragangliomas are often located in abdominopelvic regions and may be biochemically active with elevated levels of plasma metanephrines and chromogranin A, resulting in symptoms of catecholamine excess such as diaphoresis, palpitations, and headaches." (PMID 39569273, 2024).
tauopathy (2 papers, 2024 to 2025). Neurodegenerative disorders involving deposition of abnormal tau protein isoforms (tau proteins) in neurons and glial cells in the brain. "Chromogranin A (CgA) ablation in Tauopathy mice reduces toxic Tau buildup, reverses cognitive decline and improves lifespan." (PMID 40393970, 2025).
thymoma (2 papers, 2010 to 2021). A neoplasm arising from the epithelial cells of the thymus. "Even though both types of lesions share strong CAM 5.2 positivity, thymomas are negative for neuroendocrine markers (e.g. chromogranin A, synaptophysin, NCAM, and CD56) and may be useful for NECs." (PMID 21092193, 2010).
thyroid (2 papers, 2024 to 2025). "Only two studies explored chromogranin A, a precursor of catestatin, levels in thyroid disorders." (PMID 40001472, 2025).
ulcerative colitis (2 papers, 2012 to 2020). An inflammatory bowel disease involving the mucosal surface of the large intestine and rectum. "It is noteworthy that colonic chromogranin A cells have been found to increase in patients with ulcerative colitis (UC) and Crohn’s disease (CD)." (PMID 22699394, 2012).
von Hippel Lindau syndrome (2 papers, 2010 to 2023). "This patient had elevated levels of dopamine, normetanephrine and chromogranin A. One patient was known to have von Hippel-Lindau syndrome." (PMID 20863367, 2010).
abdominal aortic aneurysm (1 paper, 2021). Enlargement and ballooning of the vessel that supplies arterial blood to the abdomen, pelvis and legs. "The effects of transfection of N-terminal fragment of chromogranin A Vasostatin-1 (VS-1) nanocarriers on formation of abdominal aortic aneurysm (AAA) were discussed, and its mechanism was analyzed." (PMID 34839793, 2021).
acinar adenocarcinoma (1 paper, 2022). "The majority of the tumor was acinar adenocarcinoma–positive for PSA; however, ∼10% of the tumor showed small-cell morphology, which stained positive for chromogranin A and synaptophysin." (PMID 35487690, 2022).
ameloblastoma (1 paper, 2025). The most common odontogenic tumor, arising from the epithelial component of the embryonic tooth and usually affecting the molar-ramus region of the mandible or maxilla. "Immunohistochemically, ameloblastomas often express CD56; however, novel neuroendocrine markers such as synaptophysin (SYP), insulinoma-associated protein 1 (INSM1), and chromogranin A (CgA) remain unexplored." (PMID 39937015, 2025).
Ascites (1 paper, 2022). Accumulation of fluid in the peritoneal cavity (between the layers of the peritoneum that lines the abdomen). "Furthermore, Chromogranin A of ≥ 4 × ULN, pre-existing ascites and presence of unusual sites of metastases were significantly associated with shorter PFS." (PMID 34110489, 2022). "Elevated chromogranin A of ≥ 4 × ULN and the presence of pre-existing ascites have a negative impact on both PFS and OS." (PMID 34110489, 2022). "We found that OS was inversely related to non-GEP-NETs, chromogranin A of ≥ 4 × ULN, pre-existing ascites, development of interim ascites, high tumor burden within the liver of > 50% liver volume and five or more bone metastases." (PMID 34110489, 2022).
babesiosis (1 paper, 2018). Babesiosis refers to a condition caused by microscopic parasites that infect the red blood cells. "On the other hand, a higher number of phosphorylated proteins was found in control samples in case of ApoA1 at S220 (5 controls vs. none in babesiosis samples), Chromogranin A at S190 (4 controls vs. 1 babesiosis) and Fibrinogen α at S22 (9 controls vs. 6 babesiosis)." (PMID 30485286, 2018).
bile duct adenoma (1 paper, 2014). A benign, well-demarcated polypoid neoplasm arising from the bile duct epithelium. "By immunohistochemistry, clear cell bile duct adenomas are positive for CK7, CEA, and EMA and are negative for CK20, HepPar-1, chromogranin A, prostate specific antigen (PSA), and vimentin." (PMID 24955270, 2014).
Brain atrophy (1 paper, 2014). Partial or complete wasting (loss) of brain tissue that was once present. "Lower levels of vascular endothelial growth factor and chromogranin A (CrA) were associated with higher whole brain atrophy." (PMID 25072324, 2014). "Lower levels of Chromogranin-A (CgA) were associated with higher whole brain atrophy (0.008) and ventricular expansion (0.009) after adjusting for baseline volumes and t-tau and predicts higher whole brain atrophy (P=0.009) after additionally adjusting for p-tau, age, ApoE status and sex." (PMID 25072324, 2014).
bronchial NET (1 paper, 2018). "From a diagnostic point of view, all patients with bronchial NET should have plasma chromogranin A levels assessed, which never happened in our patient series." (PMID 30228817, 2018).
carcinosarcoma (1 paper, 2021). A malignant tumor composed of a mixture of carcinomatous and sarcomatous elements. "In addition, carcinoma cells with a cord-like or trabecular arrangement similar to that seen in endocrine carcinoma expressed chromogranin A. An 84-year-old man was diagnosed with carcinosarcoma in the esophagus and stomach." (PMID 33761637, 2021).
chemodectoma (1 paper, 2023). "Synaptophysin and chromogranin A were the most useful immunohistochemical markers to diagnose malignant chemodectoma in this cat." (PMID 37533454, 2023).
cholangiocellular carcinomas (1 paper, 2010). "Five hepatic carcinoids (11%) positive for one or more neuro-endocrine differentiation markers (chromogranin-A, neuron-specific enolase, and synaptophysin) and three cholangiocellular carcinomas (7%) were not further analysed in this study." (PMID 20167095, 2010).
chronic heart failure (1 paper, 2021). "Likewise, we have previously demonstrated that decreased vasostatin-2, a peptide derived from chromogranin A possessing pronounced anti-inflammatory and anti-atherogenic actives, was associated with chronic heart failure and incidence of major adverse cardiac events during a 3-year follow-up." (PMID 35004878, 2021).
chronic renal failure (1 paper, 2017). "Furthermore, levels of circulating Chromogranin A can be elevated in the setting of proton pump inhibitor use and in a number of non-malignant conditions including chronic renal failure and hepatic disease." (PMID 28903345, 2017).
Cowden Syndrome (1 paper, 2015). "Until such data become available, we recommend that patients with Cowden Syndrome, as part of their routine control, have an annual chromogranin A measurement to screen for NET development." (PMID 26798346, 2015).
Cushing syndrome (1 paper, 2023). Cushing's syndrome (CS) encompasses a group of hormonal disorders caused by prolonged and high exposure levels to glucocorticoids that can be of either endogenous (adrenal cortex production) or exogenous (iatrogenic) origin. "Immunohistochemically, all tumors were diffusely positive for CK18 and synaptophysin, while chromogranin A was diffusely expressed in both Cushing syndrome-associated RenNETs and in 3/11 non-functioning RenNETs." (PMID 37405461, 2023).
end stage renal failure (1 paper, 2020). "Two of these patients also had elevated chromogranin A results, but these were probably caused by co-existing end stage renal failure." (PMID 33391185, 2020).
endometrial carcinoma (1 paper, 2022). A malignant tumor arising from the epithelium that lines the cavity of the uterine body. "Incidentally, her endometrial carcinoma was also positive for CD56 and chromogranin A. Human papillomavirus DNA typing analysis of vulvar tumor was negative." (PMID 35351092, 2022).
esophageal small-cell carcinomas (1 paper, 2021). "Synaptophysin immunoreactivity was detected in all esophageal small-cell carcinomas, whereas chromogranin A was expressed in 10 (67%) esophageal small-cell carcinomas." (PMID 32556556, 2021).
gangliocytoma (1 paper, 2025). A well differentiated, slow growing neuroepithelial neoplasm composed of neoplastic, mature ganglion cells. "Histopathology revealed a biphasic tumor composed of small monomorphic nests and solid sheets of pitNET cells (synaptophysin and chromogranin A positive, S100 negative) and large voluminous eosinophilic cells of the gangliocytoma component (synaptophysin, chromogranin A and S100 positive)." (PMID 41522407, 2025).
gastric neuroendocrine neoplasm (1 paper, 2025). A neoplasm with neuroendocrine differentiation that arises from the stomach. "Gastric neuroendocrine neoplasms typically exhibit positive immunohistochemical staining for chromogranin A, synaptophysin, and INSM-1." (PMID 40248085, 2025).
hepatoblastoma (1 paper, 2022). Hepatoblastoma (HB) is a malignant hepatic tumor and is the most common pediatric liver cancer. "We identified high levels of IGF2 in patients enriched for Hepatoblastoma I and Hepatoblastoma II signatures, GATA1 in patients enriched for the Erythroid-like signature, POSTN in patients enriched for the DCN-high signature, and CHGA in patient 8 who was enriched in the Neuroendocrine signature." (PMID 36008377, 2022).
hyperparathyroidism (1 paper, 2023). Hyperfunction of the parathyroid glands resulting in the overproduction of parathyroid hormone. "This revealed mild normocalcemic hyperparathyroidism in two patients (cases #4 and #5), mildly elevated serotonin in three patients (cases #4,5,6), and high levels of Chromogranin A and 5-HIAA in one (case #6)." (PMID 37152923, 2023).
invasive lobular carcinomas (1 paper, 2014). "Chromogranin A was negative in all of the 25 cases (including 9 invasive lobular carcinomas)." (PMID 24701575, 2014).
Lymphatic Metastasis (1 paper, 2025). Transfer of a neoplasm from its primary site to lymph nodes or to distant parts of the body by way of the lymphatic system. "Only 6 genes, namely CHGA, CHGB, PCSK2, PCSK1N, DLGAP1 and DLGAP3 were down-Regulated in the lymphatic metastasis group." (PMID 41431044, 2025).
Malignant Paraganglioma (1 paper, 2017). A paraganglioma that metastasizes to regional or distant anatomic sites. "In our case, vascular invasion and increased number of mitoses were observed and also the tissue was positive for chromogranin A. Malignant paraganglioma is a rare presentation diagnosed by local recurrence after total resection of the primary mass or findings of distant metastasis." (PMID 29255564, 2017).
meningioma (1 paper, 2026). A generally slow growing tumor attached to the dura mater. "We aimed to explore neuroendocrine differentiation in meningiomas by investigating the following neuroendocrine markers: neural cell adhesion molecule (CD56/NCAM), chromogranin A, chromogranin B, chromogranin C, neuron-specific enolase (NSE), secretagogin, and synaptophysin." (PMID 41769706, 2026). "Our study does not support the hypothesis of neuroendocrine differentiation in meningiomas, as chromogranin A and synaptophysin were mostly absent." (PMID 41769706, 2026).
Nephroblastoma (1 paper, 2025). An embryonal neoplasm characterized by the presence of epithelial, mesenchymal, and blastema components. "Positive staining for neuroendocrine markers (NSE, synaptophysin, chromogranin A) and negative staining for lymphoid (CD3, Pax5) and nephroblastoma (WT1) markers were pivotal in confirming the tumor’s neuroendocrine origin." (PMID 40948633, 2025).
neurocytomas (1 paper, 2022). "Immunohistochemistry confirmed that neurocytomas are positive for neuronal differentiation markers such as synaptophysin and chromogranin A and variable neurofilaments, NeuN and calretinin." (PMID 35663322, 2022).
Neuroendocrine prostate carcinoma (1 paper, 2023). "Neuroendocrine prostate carcinoma (NEPC) is recognized by neuroendocrine markers such as chromogranin A (CgA), synaptophysin (Syn), and neuron-specific enolase (NSE)." (PMID 38077153, 2023).
NUT carcinoma (1 paper, 2024). "Synaptophysin was positive by immunohistochemical analysis for some NUT carcinoma cases; however, no cases were positive for chromogranin A or CD56." (PMID 38326851, 2024).
oncocytoma (1 paper, 2020). "Histopathological examination revealed an oncocytoma of uncertain malignant potential with a low Ki-67 proliferation index, inhibin A positivity, and chromogranin A negativity." (PMID 33062350, 2020).
ovarian serous adenocarcinoma (1 paper, 2023). An adenocarcinoma that arises from the ovary and is characterized by the presence of malignant epithelial cells that, in well differentiated tumors, resemble the epithelium of the fallopian tube or, in poorly differentiated tumors, show anaplastic features and marked nuclear atypia.
periodontal diseases (1 paper, 2023). "Salivary cortisol and chromogranin A levels increased with the severity of periodontal disease." (PMID 37113482, 2023). "Moreover, salivary cortisol and chromogranin A levels increased with the severity of periodontal disease." (PMID 37113482, 2023).
polycystic ovary syndrome (1 paper, 2025). A disorder that manifests as multiple cysts on the ovaries. "This study investigates serum chromogranin A (CgA) levels and their association with endocrine and metabolic features in patients with polycystic ovary syndrome (PCOS)." (PMID 41480370, 2025). "In this study, we demonstrated that serum chromogranin A (CgA) levels were significantly elevated in women with polycystic ovary syndrome (PCOS) and showed a positive correlation with body mass index (BMI), insulin, glucose, HOMA-IR, and high-sensitivity C-reactive protein (hs-CRP)." (PMID 41480370, 2025).
polyp (1 paper, 2024). A usually exophytic mass attached to the underlying tissue by a broad base or a thin stalk. "Factors such as older age and elevated levels of gastrin and chromogranin A were linked to polyp development." (PMID 39632655, 2024).
primary biliary cirrhosis (1 paper, 2016). "In chronic biliary diseases such as primary biliary cirrhosis (PBC) and primary sclerosing cholangitis (PSC), DRs are prominent and composed mostly of cells expressing biliary (Cytokeratins 7 and 19), neuroendocrine (NCAM, Chromogranin A), and stem cell markers (Sox9, CD133)." (PMID 26880956, 2016).
prion disease (1 paper, 2020). A transmissible disease that is caused by a protein that is able to induce abnormal folding of normal cellular proteins, leading to characteristic spongiform brain changes, which are associated with neuronal loss without an inflammatory response. "Further research is still required to elucidate the molecular pathways in which BAMBI and CHGA could be participating in prion disease-related conditions." (PMID 32370154, 2020).